TNF (tumor necrosis factor)
Diseases named in the same sentence as TNF in open-access papers (continued):
Sharing a sentence is not in itself a finding about the gene and the disease.
cerebral malaria (114 papers, 2005 to 2025). A sequestration of Plasmodium falciparum in the brain, which can cause coma and/or seizures. "Excess tumor necrosis factor (TNF) is implicated in the pathogenesis of hyperinflammatory experimental cerebral malaria (eCM), including gliosis, increased levels of fibrin(ogen) in the brain, behavioral changes, and mortality." (PMID 38115011, 2023). "Supporting the relevance and importance of the hyperinflammatory model, the balance of pro-inflammatory and regulatory cytokines, namely TNF and IL-10, and genetic variants in these genes, correlate with severity in human cerebral malaria." (PMID 38115011, 2023). "Although the results suggested that that TNF-α level is associated with cerebral malaria, the evidence is inconsistent and imprecise." (PMID 32576141, 2020). "In this way, this systematic review aimed to gather clinical evidence of the association of cerebral malaria by Plasmodium falciparum and TNF-α level increasing in humans." (PMID 32576141, 2020). "This systematic review aimed to investigate the association between TNF-α levels and cerebral malaria." (PMID 32576141, 2020). "In this systematic review, we gathered evidence of the association between Cerebral Malaria and TNF-alpha levels." (PMID 32576141, 2020). "Although there are variations in the reports on cytokine roles in cerebral malaria, the secretion of TNF-α has been well associated with neurological symptoms." (PMID 31878288, 2019). "Polymorphisms in genes encoding such cytokines as the tumor necrosis factor (TNF-α) and the increased risk of cerebral malaria has been documented." (PMID 30118498, 2018). "Specifically, TNF and TGFβ1 were predicted to regulate the cerebral malaria-associated proteins in MVs." (PMID 28599650, 2017). "In one of those vanguard studies, McGuire and colleagues showed that mutation at position -308 of the TNF promoter region is associated with increased risk of death from cerebral malaria in Africa." (PMID 26858717, 2016). "High concentrations of TNF are related to the pathogenesis of symptoms associated with malaria infection, such as fever and severe forms of infection, such as cerebral malaria." (PMID 25124540, 2014). "Elevated levels of IFN-γ, TNF, IL-12, IL-6, IL-1β, and IL-10 are initially protective, although excessive serum levels of these cytokines are associated with cerebral malaria pathology." (PMID 22336003, 2012). "In Gambia, the SNPs TNF −308G>A (rs1800629) and TNF −238G>A (rs361525) were associated with an increased risk of cerebral malaria and severe malarial anemia, respectively." (PMID 23316245, 2012). "A major outcome of monocyte activation is elaboration of inflammatory mediators such as TNFα and IL-6, each of which has been shown to be necessary or associated with cerebral malaria." (PMID 20454664, 2010). "Association between TNF/LTα polymorphism and increased risk of cerebral malaria has been reported, however more investigations are necessary to fully decipher the molecular bases of the link between disease manifestation and TNF/LTα polymorphism." (PMID 18612394, 2008). "The promoter allele of TNF-α gene (TNFA), TNFA -308A, was reported to be associated with susceptibility to cerebral malaria in Gambia." (PMID 16098232, 2005). "Cerebral malaria in P. berghei ANKA-infected mice increases the levels of miR-27a, miR-142, and miR-223 when compared to P. yoelii-infected mice; these miRNAs are implicated in TNF signaling and monocyte sequestration in cerebral microvessels in cerebral malaria." (PMID 31906500, 2020). "In this way, this systematic review could bring clarification on the association between TNF-α level and cerebral malaria." (PMID 32576141, 2020). "Some T helper 1 (Th1) cytokines (e.g., IFN-γ, lymphotoxin, and TNF) have been implicated in driving the immunopathological process leading to cerebral malaria, whereas some Th2 (e.g., IL-10, transforming growth factor (TGF)-β) cytokines appear to inhibit this process." (PMID 31262018, 2019).
cerebral malaria (continued). "Interestingly, IFNγ and TNFα have been linked to cerebral malaria progression by acting on brain endothelial cells, thus promoting their activation and/or apoptosis." (PMID 31223430, 2019). "In relationship to disease, TNF polymorphisms are associated with susceptibility to a range of infectious diseases including mucocutaneous leishmaniasis, Chlamydia trachomatis, cerebral malaria, and lepromatous leprosy." (PMID 25479081, 2014). "Higher levels of TNF have been observed in cerebral malaria and correlated with mortality, and genetic predisposition to overproduce TNF in response to infection has been associated with susceptibility to cerebral malaria." (PMID 21772838, 2012). "TNF, superoxide, and free heme (caused by hemolysis) are all elevated in cerebral malaria and may contribute to the neuronal damage detected in brains of cerebral malaria patients." (PMID 21772838, 2012). "Furthermore, TNF P-D allele has been shown significantly associated with cerebral malaria in our previous study in Karen and Burmese populations." (PMID 20846452, 2010). "Three SNPs of TNF promoter -857, -863 and -1031 were analyzed and the frequency of the designated allele -857C/-863C/-1031C was found to be significantly higher in patients with cerebral malaria than that with UM in area along Thai-Myanmar border." (PMID 20846452, 2010). "At low levels, TNF is believed to augment parasite killing by macrophage activation and subsequent release of cytokines, whereas high TNF level has been associated with severe manifestations like acute respiratory distress and cerebral malaria." (PMID 18194515, 2008). "However, even in the face of the association results presented by most of the selected articles, the low level of evidence presented by them does not offer certainty of the results regarding the association of TNF-alpha with cerebral malaria, according to GRADE criteria." (PMID 32576141, 2020). "The ability of sICAM-1 to elicit inflammatory responses could also mediate an increased production of pro-inflammatory cytokines such as TNF-α, whose overproduction has been implicated in pathogenesis of CM as postulated by the inflammatory hypothesis of cerebral malaria development." (PMID 24386348, 2013). "Increasing pro-inflammatory cytokines like TNF-α and IF-γ, as well as certain interleukins like IL-6, IL-10, and IL-12, is probably a key to the etiology of cerebral malaria." (PMID 39204168, 2024). "Similar outcomes were observed in a mouse model where high proportions of Vγ9Vδ2 T cells were associated with increased plasma levels of pro-inflammatory cytokines, notably TNF alpha and IFNγ, leading to cerebral malaria." (PMID 38827744, 2024). "P. falciparum-infected red blood cells and inflammatory cytokines, like tumor necrosis factor alpha (TNF-α), have been implicated in the development of cerebral malaria, but it is still unclear how they contribute to the loss of BBB integrity." (PMID 36036514, 2022). "Because cytokines TNF-α and IL-1β contribute to cerebral malaria pathogenesis in mice, we also evaluated the effect of 17β-estradiol on the mRNA expression of pro-inflammatory cytokines in the brain." (PMID 33841336, 2021). "The degree of brain swelling was independent of plasma levels of IL-1β, IL-6, IL-8, and IL-10 in children with cerebral malaria, while IL-12 and TNF were elevated in patients with more severe edema." (PMID 33391257, 2020). "Animals infected with Plasmodium berghei ANKA, a cerebral malaria model, show a five-fold increase in plasma TNF concentration and an increase of ten times in IFN-γ levels." (PMID 31234939, 2019). "For example, high TNF-α production is a strong predictor of severe malarial anemia and cerebral malaria in children." (PMID 31497025, 2019).
cerebral malaria (continued). "Proinflammatory responses mediated by TNF-α in the CNS trigger the pathogenesis of cerebral malaria by partly contributing to the induction of endothelial activation, increased blood–brain barrier permeability, and neuroinflammation." (PMID 31878288, 2019). "An earlier study has reported that interaction with ICAM-1 contributes to increased serum TNF-α in cerebral malaria model of P. berghei ANKA-infected mice and that ICAM-1 deficient mice survive >15 days compared to 6–8 days in wild type (WT) mice." (PMID 30619355, 2018). "A useful parameter in cerebral malaria is the low ratio of anti-inflammatory cytokine IL-10 to pro-inflammatory cytokine TNF-α and low level of anti–GPI antibody in plasma." (PMID 29409517, 2018). "Litterature revue shows that the gravity of cerebral malaria could be explained by the sequestration of invaded red blood cell in a tissus, causing vital dysfonction in the concerned organ for exemple the production of cytokines (TNF, IFN) which may cause the release of carbon monoxyde." (PMID 30061962, 2018). "In the previous studies, the association of various plasma detectable markers (PCT, CRP, ICAM, ANG2, TNFα and IP-10) with mortality in patients with severe or cerebral malaria have been reported." (PMID 30286756, 2018). "In the present work, we evaluated the mRNA expression of both IFN-γ and TNF-α in different brain areas because these cytokines are involved in both parasite elimination and development of cerebral malaria." (PMID 30515051, 2018). "The increased immune response, involving CD8+ T cell and macrophage recruitment and the expression of pro-inflammatory cytokines, such as IFN-γ, TNF-α and Lymphotoxin (LT)-α, is central to the development of cerebral malaria, in both human and mice." (PMID 28448579, 2017). "Cognitive impairment in human cerebral malaria was associated with high cytokine levels in the cerebrospinal fluid (CSF) including IL-6, CXCL-8/IL-8, G-CSF, TNF-α and IL-1Ra, whereas a correlation between serum and CSF levels was only found for G-CSF." (PMID 28448579, 2017). "According to previous studies, the ratio of anti‐inflammatory (IL‐10) to inflammatory (TNF‐α) is a potentially useful parameter indicator in cerebral malaria." (PMID 27042299, 2016). "One of the primary mediators of this inflammatory response is TNFα; decreases in TNFα have been consistently shown to improve the outcome of cerebral malaria." (PMID 26599510, 2015). "Abca1-/- mice have fewer pro-inflammatory microparticles in plasma and, decreased brain TNFα compared with wild-type littermates, and are protected from cerebral malaria." (PMID 26599510, 2015). "There is accumulating evidence that the pathogenesis of cerebral malaria is due to an immune-pathological reaction giving rise to excessive production of cytokines such as tumor necrosis factor-alpha (TNF-α) and interferon gamma (IFN-γ)." (PMID 25886020, 2015). "Activation of brain endothelial cells, infected red cells and circulating leukocytes by both IFN-γ and TNF during cerebral malaria most likely triggers the cascade of events that swiftly transforms the brain microenvironment." (PMID 23613965, 2013). "Further, inhibitory effect of TNF-α on erythropoiesis and subsequent severe malarial pathogenesis has been demonstrated in human and mouse model of experimental cerebral malaria (ECM)." (PMID 23110190, 2012). "CNI-1493 prevented infected mice from experimental cerebral malaria by decreasing the levels in hypusinated eIF-5A and serum TNF, implicating a link between cytokine signaling and the hypusine pathway." (PMID 22694849, 2012). "The inflammatory cytokine TNF-α is associated with cerebral malaria, and it is possible that the bias against producing a Th1 response in young children - whether it is due to inherent age-related properties or exposure and environment - helps to protect them from developing cerebral malaria." (PMID 22394452, 2012).
cerebral malaria (continued). "TNF-α is a proinflammatory cytokine that has attracted particular interest because of its ambiguous activity in host defense and pathogenesis of cerebral malaria and other serious complications." (PMID 23316245, 2012). "Other immunomodulatory therapies tested in cerebral malaria in the past (e.g., anti-TNF antibodies, dexamethasone) have failed." (PMID 21772838, 2012). "An excessive inflammatory response with elevated levels of pro-inflammatory cytokines, especially TNF, is a major contributor to cerebral malaria pathology." (PMID 21772838, 2012). "Two gene promoter polymorphisms of TNF-α (homozygosity for the TNF-308A and alleles of TNF-376A) have been associated with cerebral malaria in children in Gambia and Kenya (Africa)." (PMID 23209898, 2012). "Activated CD4+ T lymphocytes stimulate macrophages to produce TNF-alpha, which leads to cerebral malaria in mouse models." (PMID 19680452, 2009). "In experimental murine malaria the administration of TNF neutralizing antibodies prevented experimental cerebral malaria (ECM)." (PMID 18612394, 2008). "In our study, 62.5% (5/8) of patients who died from cerebral malaria presented simultaneously high TNFα concentrations and high anti-brain reactivity levels." (PMID 17460756, 2007). "As mice begin to show symptoms of cerebral malaria, there is a significant increase in the number of cells with morphological characteristics of microglia and astrocytes expressing TNF, which along with systemic TNF, induces permeability of the blood brain barrier (BBB)." (PMID 38115011, 2023). "In addition to TNF, the cytokines IFN-γ and IL-17A have also been associated with an increased risk of developing cerebral malaria." (PMID 38256880, 2023). "Cerebral malaria was found to have high levels of TNF-α in fatal outcomes." (PMID 32264832, 2020). "Here, plasma and cerebral TNFα and IL-6 production was markedly diminished by TRPV1 ablation, thus evidencing, once more, that TRPV1 signaling is involved in the tissue damage associated with cerebral malaria." (PMID 31223430, 2019). "However, TNF blockade has thus far proven ineffective in preventing death in childhood cerebral malaria." (PMID 29866139, 2018). "As anti-TNF blocks many components of the acute phase reaction besides coagulation, we proceeded with more specific tests for the importance of coagulation to hyper-inflammatory experimental cerebral malaria." (PMID 29866139, 2018). "This text developed from our view that the riddle of malarial encephalopathy (cerebral malaria, (CM)) could be understood only by getting engrossed in understanding how TNF influences brain function in other states, such as AD." (PMID 28451786, 2017). "The ability of IFN- to stimulate macrophages to release factors such as TNF may be related to its role in cerebral malaria, since antibodies to IFN- have been reported to prevent experimental cerebral malaria in mice (Richards, 1997 ▶)." (PMID 27222837, 2016). "Decreases in TNFα have been consistently shown to improve the outcome of cerebral malaria." (PMID 26599510, 2015). "In the early stage after the onset of neurological symptoms (day 12 post infection), curcumin, AE (650 μg) and AC-treated animals showed inhibition of P. berghei 18S rRNA, CXCL10 and TNFα mRNAs, similar to the results obtained when curcumin was given before the onset of cerebral malaria symptoms." (PMID 26227888, 2015). "In both humans and mouse models, high levels of TNF are correlated with cerebral malaria." (PMID 25192715, 2014). "We also reported that the frequency of some TNF alleles were significantly greater in patients with cerebral malaria than in patients with non-cerebral malaria." (PMID 22412373, 2012). "Previous studies indicate that tumour necrosis factor (TNF) and lymphotoxin alpha (LTα) may be important for the development of cerebral malaria (CM) and other SM syndromes." (PMID 21029472, 2010).
cerebral malaria (continued). "Among these cytokines, TNF is thought to play a major role in pathogenesis of cerebral malaria." (PMID 20846452, 2010). "Proinflammatory (Th1) cytokines such as TNF-alpha are thought to play an important role in malaria pathogenesis and in cerebral malaria in particular, as they increase surface expression of adhesion molecules on endothelial cells, promoting parasite attachment." (PMID 19680452, 2009). "In patients with cerebral malaria disease severity has been correlated with TNF serum levels." (PMID 18612394, 2008). "Also, Th1-type pro-inflammatory cytokines, such as IFN-γ and TNF are thought to play an important role in the both protecting against and increasing the pathogenesis of cerebral malaria." (PMID 17204149, 2007). "Notably, myeloid-specific JUNB deletion in cerebral malaria models reduces IL-1β/TNF production and shifts macrophages toward a regulated phenotype, improving survival, a finding that dovetails with our observation that JUNB silencing suppresses M1 polarization and NF-κB activation." (PMID 40917776, 2025). "Furthermore, some of the hits such as adalimumab, Natalizumab, etanercept, thalidomide, ustekinumab, and canakinumab are anti-TNF monoclonal antibodies and anti-inflammatory agents that could modulate the immune response to severe and cerebral malaria." (PMID 34702263, 2021). "Furthermore, transfer of MVs from TNF-stimulated endothelial cells induced brain histopathology similar to cerebral malaria, indicating MVs might be active contributors to the pathologies associated with severe malaria." (PMID 28599650, 2017). "Similarly, IFN-γ and TNF are necessary for disease in the murine model of cerebral malaria." (PMID 22336003, 2012). "Thus TNF may play some role, such as ensuring sufficient receptor expression for efficient cytoadherence, but that progression to severe disease such as cerebral malaria requires other factors for its aetiology." (PMID 22043276, 2011). "A decrease in the Th1: Th2 ratio could be related to the observed resistance in obese mice because cerebral malaria due to P. berghei ANKA involves the Th1 cytokines TNF-α and INF-γ in the regulatory cascade controlling inflammatory responses after malarial infections." (PMID 18489748, 2008). "Interestingly, the strong increase in brain CD8+ T cells seen in wild type or TNF deficient mice that develop cerebral malaria was essentially absent in PbA-infected LTβR or LTβ deficient mice." (PMID 18612394, 2008). "Exosomes from P. falciparum activate microglia derived from human monocytes, increasing the gene expression levels of the inflammatory cytokine tumor necrosis factor alpha (TNF-α), reducing IL-10 expression, and enhancing neuroinflammation in cerebral malaria." (PMID 39204224, 2024). "In the case of experimental cerebral malaria, the authors found a higher mRNA expression of the pro-inflammatory cytokines IL-2, IL-6, IL-10, IL-17, IFN-γ, and TNF in the serum, hippocampus, and frontal cortex in mice infected with Plasmodium berghei." (PMID 39057789, 2024). "Cerebral malaria is the most severe form of infection with Plasmodium falciparum characterized by a highly inflammatory response (IFN-γ, IL-1β, TNF-α, iNOS, and IL-6), which contributes to severity of the disease." (PMID 34975479, 2021). "Tumor necrosis factor-α (TNF-α) is involved in the pathogenesis of several diseases, including cerebral malaria, characterized by high levels of this cytokine." (PMID 33801073, 2021). "Although pro-inflamatory responses involving cytokines including TNF-α, IFN-γ have been identified as contributors to the pathology of cerebral malaria in mice, early production of IFN-γ has been found to be crucial for preventing cerebral malaria." (PMID 29970128, 2018). "Abca1-/- mice survive cerebral malaria after P. berghei ANKA infection and have significantly lower levels of TNFα than wild-type mice." (PMID 26599510, 2015).